GFAP (glial fibrillary acidic protein)
Diseases named in the same sentence as GFAP in open-access papers (continued):
Sharing a sentence is not in itself a finding about the gene and the disease.
glioma (continued). "We have also validated the co-expression of METTL8 and GFAP in gliomas, and the results indicate that METTL8 might be involved in the localized expression of GFAP." (PMID 38824202, 2024). "A brain lesion biopsy revealed a high-grade infra-tentorium IDH-1 and IDH-2 wild-type glial tumor, GFAP and Olig2 positive and histone H3‐K27M mutation-negative (glioblastoma, grade 4 WHO 2021)." (PMID 37692853, 2023). "The expression of GFAP was observed in all obtained glioma cultures." (PMID 37375743, 2023). "Interestingly, this model also aggregates the glioma cases by sub-type, with glioblastomas having high GFAP, meningiomas having low GFAP and high FABP4, while anaplastic astrocytomas and oligodendrogliomas display both low FABP4 and low GFAP." (PMID 36959545, 2023). "GFAP negativity depends mainly on glioma histological origin or other factors." (PMID 36831736, 2023). "Reactive astrocytes express high levels of glial fibrillary acidic protein (GFAP) and support parenchymal infiltration and uncontrolled proliferation of glioma cells by expressing matrix metalloproteinase‐2 (MMP2) and secreting stromal cell–derived factor‐1 (SDF1), respectively." (PMID 36300592, 2023). "Laminins can be produced by GFAP positive cells during glioma cell invasion in humans." (PMID 36980765, 2023). "GFAP and a handful of other plasma biomarkers may be useful for early glioma detection and probably, prognosis." (PMID 36959545, 2023). "Serum-induced differentiation of GSCs is associated with loss of tumorigenicity and differentiated glioma cells (DGCs) expressed low levels of the GSC marker SOX2 and BMI1 as well as high levels of astrocytes marker GFAP, which is consistent with previous studies." (PMID 37980347, 2023). "The key points of diagnosis are the reticular fibres in sarcoma and GFAP expression in glioma." (PMID 36756387, 2023). "It should be emphasized that the correlation between hsa_circ_0004214 and GFAP may be interfered by the source of glioma tissue." (PMID 36831736, 2023). "Human glioma cells served as a positive control for human NeuN or human GFAP." (PMID 35328574, 2022). "GFAP is quite characteristic of gliomas and has been detected in blood and used to differentiate primary tumors from metastases or and to differentiate glioma subtypes." (PMID 35693015, 2022). "Deciphering whether A2B5 could be expressed by the GFAP+ NSCs of the SVZ would be crucial information in favor of A2B5+ cells as candidates to be at the origin of gliomas." (PMID 35563061, 2022). "It is now suggested that discriminating between predominant GFAP isoforms, GFAPδ or GFAPα, is useful for assessing the malignancy state of astrocytoma, and may even contribute to the classification of gliomas." (PMID 35372061, 2022). "It is currently unknown exactly how the levels of serum GFAP relate to glioma properties and whether current methods are sensitive or selective enough to use GFAP as a blood-based biomarker for astrocytic tumours." (PMID 35919979, 2022). "Furthermore, immunohistology of tissues using an anti-POX antibody showed that normal glial (para-tumor) tissues that were GFAP-positive exhibited strong immunostaining, while few signals were noted in the glioma samples." (PMID 33508123, 2021). "High-grade gliomas (N = 145), brain metastasis (N = 21) and large stroke patients (>100 cm3) (N = 3 versus 6; multiple time points) had significantly increased frequencies of glial fibrillary acidic protein+CD16+ monocytes compared to healthy controls." (PMID 33501422, 2021). "Interestingly, D.stramonium seed agglutinin were found to enhance the expression of GFAP, which provides them anticancer potential against gliomas." (PMID 34439539, 2021).
glioma (continued). "Immunocytochemical staining of dissociated gliomas revealed GFAP-carrying (GFAP+) CD68+ cells." (PMID 33501422, 2021). "In addition, we found that expression of the astrocytic marker GFAP, which is also expressed in glioma cells, is different between LN-18 and U-87 MG cells." (PMID 34681783, 2021). "GFAP+ glioma cells were often in apposition and surrounding BVs, compatible with the phenomenon of tumor cell motility along BV via the outer side of the basement membrane, events that are compatible with previous observations seen in glioma mouse models." (PMID 33579378, 2021). "Moreover, the cell morphology of primary human glioma cells, U251-MG and U87-MG cells were evaluated through the label of GFAP and S100B proteins." (PMID 34422645, 2021). "Measurement of GFAP-carrying monocytes could thus be applied in clinical trials and decision making in glioma, brain metastases and AIS, thereby significantly changing diagnostics in neurology and oncology." (PMID 33501422, 2021). "Moreover, malignancy of gliomas correlates inversely with the concentration of glial fibrillary acidic protein (GFAP)." (PMID 34439539, 2021). "These tumors expressed high levels of glioma markers GFAP, hNES, Ki67, and pERK." (PMID 33390587, 2021). "GFAP is a marker of astrocytes and is widely expressed in most CNS brain tumors Of course, GFAP was expressed in 85.7% of NT and higher GFAP positivity was found in glioma than other types of NT (P value < 0.05)." (PMID 33208163, 2020). "GFAP is a useful marker for glioma and was also positive in neuroepithelium." (PMID 32064359, 2020). "We included into the custom set three probes for genes expressed in glioma tumors (GFAP, OLIG2 and PMP2), in addition to the CNS HGNET-BCOR marker probes, and performed hybridization in the series of 27 tumors originally diagnosed as HGG and one HGG relapsed sample." (PMID 32650833, 2020). "Clinical reports demonstrate that some NS patients with PTPN11 mutations have low-grade glial tumors, including dysembryoplastic neuroepithelial tumors and pilocytic astrocytomas, that p-ERK level is elevated and glial fibrillary acidic protein (GFAP) is strongly expressed." (PMID 32493428, 2020). "Ki67, S100, and GFAP are also the common protein targets for gliomas." (PMID 33014836, 2020). "In the literature, a high GFAP expression is likely to be found in low grade gliomas." (PMID 33014836, 2020). "The tumor at this stage was not easily distinguishable from nontumor tissues without YFP immunohistochemistry, yet both PDGFRα, an oligodendrocyte precursor cell (OPC) marker, and GFAP, an astrocyte marker, were ectopically expressed on the tumor side, indicating that the tumor is a glioma." (PMID 32573857, 2020). "In addition, analysis using an orthotopic xenograft model also indicated that GSC marker-positive GSLCs more efficiently take up BPA than differentiated GFAP-positive glioma cells." (PMID 33086625, 2020). "In addition, the levels of E-cadherin, connexin-43, and GFAP, which are abundantly expressed in astrocytes and at a low level in glioma cells, were upregulated; p-STAT3 has been found to initiate the promoter of GFAP." (PMID 33227992, 2020). "IDH1, Ki67, and GFAP were once considered as the golden triad of glioma IHC Ki67 is highly correlated to proliferation that may indicate the tumor grades and prognosis." (PMID 33014836, 2020). "GFAP and Olig2 immunopositivity suggested a glioma, but nothing more precise than that." (PMID 32002518, 2020). "Glioma cells may express the intermediate filaments vimentin, GFAP, nestin, synemin, and α-internexin." (PMID 31003495, 2019). "While the amount of vimentin and the glioma stem cell marker nestin showed a negative correlation with patient prognosis and/or glioma staging, an association of GFAP expression with staging is controversial." (PMID 31003495, 2019). "Moreover, transfection of primary cultured glioma cells with the miR‐1275 mimic prevented dbcAMP‐induced upregulation of GFAP." (PMID 31162799, 2019).
glioma (continued). "Also, recently GFAP-positive exosomes originating from astrocytomas were found in the blood and were claimed to be of help to the glioma classification." (PMID 31849688, 2019). "In addition, strong glial fibrillary acidic protein (GFAP)-positive cells appeared in the striatum of glioma-bearing mice." (PMID 31546801, 2019). "Therefore, future studies need to focus on further identifying the GFAP positive cell population and make use of the possibility to discriminate between GFAP variants that could be fruitful to diagnosis and to the understanding of the molecular basis of glioma." (PMID 30667110, 2019). "We suggest that discriminating between the GFAP isoforms GFAPδ and GFAPα will improve the accuracy of assessing the differentiation state of astrocytoma in clinical and experimental settings and will benefit glioma classification." (PMID 30667110, 2019). "However, differentiation of neural stem cells and glial cells results in an upregulation of the astrocytic marker GFAP which is also expressed in glioma cells." (PMID 29535786, 2018). "Oligodendrogliomas comprise 5 to 20% of gliomas and are characterized by the absent expression of glial fibrillary acidic protein and by the morphology and cell markers typically associated with myelin-forming cells, oligodendrocytes." (PMID 30279357, 2018). "Interestingly, D54MG glioblastoma cells lack expression of GFAP, as expected for a high malignancy grade glioma." (PMID 31106292, 2018). "However, GFAP, as a differentiated marker of glioma cells, was highly expressed in cells exposed to hyperoxia and exhibited a 3-fold increase compared with those exposed to normoxia and 12-fold compared with hypoxia." (PMID 28801626, 2017). "It was also evident that MYCN could promote the formation of glioma from GFAP-positive stem cells isolated from the forebrain ventricular zone (VZ)." (PMID 28333115, 2017). "Moreover, in the CD9+/GFAP+ subpopulation, double-positive exosomes from glioma patients appeared as a much higher percentage of CD9+ exosomes (mean = 6.8%) than in controls (mean = 0.03%), a 227-fold difference." (PMID 29383115, 2017). "The expression of S-100 is not stable in glioma, whereas GFAP is a qualitative diagnostic marker of glioma." (PMID 28347331, 2017). "The combined detection of CD9, survivin and GFAP markers on the surface of serum-derived exosomes from glioma patients by imaging flow cytometry may provide another useful tool for monitoring tumor status in patients receiving survivin-based immunotherapies." (PMID 29383115, 2017). "Here we explored the expression of GFAP in glioma spheres derived from GBM patients." (PMID 26953813, 2016). "Note that u(x) may be defined as a Heaviside function, such that glioma cells are able to differentiate only if GFAP levels exceed a critical value, xc." (PMID 27515956, 2016). "Furthermore, promoter activity, as assessed by chloramphenicol acetyltransferase activity in U251 cells (a human glioma cell line that strongly expresses GFAP), remained almost unchanged between 2.2 kb and 1.7 kb." (PMID 27571575, 2016). "We next examined the noise-induced qualitative changes in cyclin D1 and GFAP in glioma cells." (PMID 27515956, 2016). "We also compared the cross-correlation of MAOB, HiF-1α and GFAP levels among all the gliomas." (PMID 26689994, 2016). "Strikingly, overexpression of Oct4 in C6 cells was able to increase the expression of Nestin and Stat3 phosphorylation while decreasing the expression of GFAP, which suggests that Oct4 might inhibit the differentiation of glioma cells." (PMID 26381429, 2016). "Importantly, in glioma, the number of GFAP-expressing cells was reported to be inversely correlated to the level of tumor anaplasia, likely representing the content of undifferentiated, stem-like cells." (PMID 27229535, 2016). "GFAP-positive cells were widely distributed in either glioma or adjacent tissues." (PMID 26452219, 2015).
glioma (continued). "Finally, CTGF was also able to induce GFAP as well as Nestin expression in a human malignant glioma stem cell line, suggesting a possible role in the differentiation process of gliomas." (PMID 26241738, 2015). "Pathological examination after surgery confirmed that the cystic part of the tumor was a mixed glioma (oligodendrocytes-astrocytoma WHO class II) that tested positive for glial fibrillary acidic protein (GFAP) and oligodendrocyte lineage transcription factors (Oligo." (PMID 25889820, 2015). "Notch1 and GFAP were considered to be markers of differentiated glioma cells." (PMID 26563263, 2015). "Plasma GFAP may, together with plasma placental growth factor (PlGF), differentiate between radiologically suspected high-grade glioma and brain metastases." (PMID 25720744, 2015). "Activation of the β-catenin/Wnt signaling cascade during EMT was associated with suppression of E-cadherin expression, and suppressing the β-catenin pathway inhibited proliferation, induced terminal differentiation and increased the expression of GFAP in glioma cells." (PMID 26563263, 2015). "We found an increased expression of serum GFAP more prominent in glioma-bearing male rats." (PMID 26116110, 2014). "Although U251 is a human glioma cell line, control U251 cells expressed very weak GFAP." (PMID 24971310, 2014). "The GFAP promoter was chosen because GFAP is expressed in both mature astrocytes and neural stem cells (NSCs) in adult mice, both of which have been proposed to be glioma-initiating cells." (PMID 25423036, 2014). "The altered levels of the nine metabolites were closely associated with the changed functions of GFAP and MMP-9, suggesting that these metabolites could be explored as potential biomarkers for monitoring malignant transformation of glioma cells." (PMID 25163530, 2014). "The least differentiated glioma cells exhibited the lowest GFAP level." (PMID 24741354, 2014). "Importantly, the expression of glioma marker GFAP in GICs on COL4-, LAM- and FN-coated dishes was also dramatically increased within 48 hours, whereas that of cells seeded on uncoated or PLL-coated dishes was much lower." (PMID 23704872, 2013). "However, independently of their origin, glioma cells express high amounts of GFAP and vimentin, much like reactive astrocytes in other inflammatory scenarios." (PMID 23641198, 2013). "Notably, U251 glioma cells under the three culture conditions exhibited distinguishing immunoreactivity for GFAP." (PMID 24260059, 2013). "Gliomas may arise from transformed neural stem or progenitor cells and GFAP-expressing astrocytes, respectively." (PMID 23424671, 2013). "In this particular model, artificially implanted GFP+ glioma cells adopt a unipolar morphology, with the major processes closely aligned with blood vessels (BVs) and intercalated between endothelial cells and resident GFAP+ protoplasmic astrocytes." (PMID 23641198, 2013). "Additionally, we observed increased mTORC2-independent signaling effects of Rictor overexpression in gliomas from GFAP-Cre/RictorloxP/loxP mice and in cell lines established from these tumors." (PMID 23077666, 2012). "Also a lentivirus-based glioma model has been developed recently where lentiviral vectors containing activated oncogenes flanked by loxP sites were injected into GFAP-Cre transgenic mouse brains." (PMID 22348397, 2012). "Moreover, we demonstrate that mice derived from crosses between these overexpressors and those carrying a GFAP-driven constitutively active EGFR variant transgene harbor more aggressive, higher-grade gliomas consistent with hyperactivated mTORC2 signaling." (PMID 23077666, 2012).
glioma (continued). "Moreover, we demonstrate that cooperative signaling between GFAP-EGFRvIII and GFAP-Cre/RictorloxP/loxP mice leads to hyperactivated mTORC2 signaling and results in high-grade gliomas." (PMID 23077666, 2012). "In homozygous GFAP-Cre/RictorloxP/loxP mice 50% of animals developed tumors consistent with Grade I–II histopathology by 12–14 weeks and with 75% of animals succumbing to gliomas by 22 weeks." (PMID 23077666, 2012). "Furthermore, oncogenic EGFRvIII signaling appears to potentiate the in vivo proliferative capacity of GFAP-Cre/RictorloxP/loxP gliomas." (PMID 23077666, 2012). "We validated this data using a model of human orthotopic glioma injected into GFAP-GFP host mice." (PMID 22393407, 2012). "That, together with the fact that the astrocytic marker GFAP could be frequently found in human glioma tissue, made astrocytes a valid candidate to be the cell of origin for glioma." (PMID 22348397, 2012). "Besides being utilized for glioma histological characterization, astroglial marker GFAP is also recognized as an indicator of glioma differentiation, since its expression increases upon several anticancer drug treatments." (PMID 22091432, 2011). "Additionally, reactive GFAP+ astrocytes and CD11b+ microglia/macrophages form a glial border around the glioma." (PMID 21060663, 2010). "Furthermore, FasL expression mediated by pG8-FasL vectors was higher in proliferating versus growth arrested ΔGli36 human glioma cells, which correlated with the enhanced apoptosis observed in the proliferating GFAP-positive ΔGli36 cells." (PMID 20942909, 2010). "One might even expect gliomas to form in the first of these model systems, given its GFAP‐dependent distribution of genetic lesions that seem more appropriate to that tumor type." (PMID 19076778, 2009). "Therefore, investigating the role of EZH2 in regulating GFAP expression and astrocyte differentiation may offer a deeper understanding of the molecular pathways involved in glioma development and reveal promising strategies for therapeutic intervention." (PMID 40022506, 2025). "However, such concerns may be alleviated through selective inhibition using tumor-specific promoters (e.g., GFAP for gliomas) or targeted delivery systems." (PMID 40933894, 2025). "WHO classification of MPE is primarily based on histological features, with essential diagnostic criteria being defined as a “glioma with papillary structures and perivascular myxoid change or at least focal myxoid microcysts AND immunoreactivity for glial fibrillary acidic protein (GFAP)”." (PMID 40137996, 2025). "Thus, GFAP is a potential biomarker and possible therapeutic target for gliomas." (PMID 36959545, 2023). "We observed that in GEMM of gliomas, oncostreams are formed by GFP+ tumor cells, and are enriched in other tumor microenvironment cells such as ACTA2+ mesenchymal cells, IBA1+, and CD68+ tumor associated microglia/macrophages cells, Nestin+ cells and GFAP+ glial derived cells." (PMID 35750880, 2022). "However, GFAP is frequently highly expressed in mature glioma cells." (PMID 35927251, 2022). "Among them, pathway reports indicate that GFAP is involved in autophagy signal transduction mediated by molecular chaperones, which may provide insights for further research on the mechanism of GFAP in the occurrence and development of gliomas." (PMID 36081550, 2022). "Since GFAP is the principal component of intermediate filaments in astroglial cells and high-grade gliomas seem to lose GFAP expression, the increased expression could be caused by the lower density of tumor cells at the edge of the tumor as a zone of tumor infiltration." (PMID 32872409, 2020). "Ki67, S100, or GFAP may not be a reliable diagnostic biomarker for gliomas, because their roles in gliomas are still under investigations, while controversies have been observed in experiments." (PMID 33014836, 2020).